EGF (epidermal growth factor)
Diseases named in the same sentence as EGF in open-access papers (continued):
Sharing a sentence is not in itself a finding about the gene and the disease.
Hypomagnesemia (13 papers, 2015 to 2025). An abnormally decreased magnesium concentration in the blood. "In the present study, we aimed to investigate if children who were treated with CNIs developed hypomagnesemia and/or renal Mg2+ loss, and if the urinary EGF expression level is related to the fractional excretion of Mg2+ (FE Mg2+)." (PMID 29861470, 2018). "In a translational clinical setting in adults, an increased FE Mg2+ was observed in CsA-treated patients who developed hypomagnesemia associated with decreased urinary renal EGF levels." (PMID 29861470, 2018). "The mechanism by which CNIs induce hypomagnesemia is inadequately explored; however, it is likely attributed to the decreased production of epidermal growth factor (EGF), which inhibits the activation of TRPM6." (PMID 39796484, 2024). "CNI induces hypomagnesemia through urinary Mg2+ wasting by downregulating the renal expression of the epidermal growth factor (EGF) and the Mg2+ channel Transient Receptor Potential Pelastatin 6 (TRMP6) in the distal collecting tubule." (PMID 39081661, 2024). "Mutation of EGF gene also resulted in the activation of TRPM-6 type channel and thus hypomagnesemia occurred." (PMID 39026680, 2024). "CNI induce hypomagnesemia through downregulation of the renal expression of epidermal growth factor (EGF) and transient receptor potential channel melastatin 6 (TRMP6) in the distal collecting tubule, leading to Mg wasting." (PMID 34322504, 2021). "Magnesium intake did not correlate with other variables, such as the BMI z-score, sex, serum Mg levels, renal function, serum or urinary EGF concentration, or the presence of hypomagnesemia." (PMID 29861470, 2018). "Similarly, mammalian target of rapamycin (mTOR) inhibitors also produce hypomagnesemia in rats, which would be mediated, at least partly, by inhibition of epidermal growth factor (EGF)-induced regulation of TRPM6 expression, as demonstrated by in vitro studies in renal tubular epithelial cells." (PMID 40565121, 2025). "However, the stimulatory effect of EGF on TRPM6 activity could be diminished by preincubation of cetuximab, an EGFR blockade, thus affecting Mg2+ transport and leading to hypomagnesemia." (PMID 25542231, 2015).
kidney damage (13 papers, 2013 to 2025). "Several recent studies have found decreasing levels of urinary EGF to be associated with several kidney diseases and progressive kidney damage." (PMID 37298105, 2023). "Methylation probes associated with kidney damage and functional decline enrich on kidney regulatory regions and associate with gene expression changes, including epidermal growth factor (EGF)." (PMID 31165727, 2019). "We observed that tubular injury scores and SUN levels were high and reaching uraemic levels after HgCl2 injection, but as predicted EGF-treated groups were protected from such kidney damage." (PMID 25389045, 2015). "Our research group and others reported that hypomagnesemia in calcineurin inhibitor (CNI)-induced nephropathy is related to the downregulation of epidermal growth factor (EGF) and TRPM6." (PMID 23457647, 2013). "Previous studies have demonstrated the role of EGF/EGFR in various nephropathies." (PMID 33921219, 2021). "The transactivation of EGFR increases the possibility of EGF/EGFR being involved in the nephropathy related to TKIs, since the metabolites of the damaged endothelial cells may lead to podocyte injury through this way." (PMID 33921219, 2021). "Our results are in line with the hypothesis that EGF influences the renal expression or activation of TRPM6 and plays a significant role in Mg2+ loss in medication-induced nephropathy." (PMID 23457647, 2013). "Our data rather suggest a chronic state of hemodynamic overload in the glomerular microcirculation, where the decrease in urinary EGF could be interpreted as an early sign of beginning latent glomerular changes (podocyte detachment) preceding initial signs of kidney damage." (PMID 36996194, 2023). "Among the 9,628 participants with available urinary kidney damage biomarker data in Uppsala (n = 4,717) and Malmö (n = 4,911), KIM-1 and EGF were only available in Uppsala, whereas osteopontin and DKK-3 were measured both in Uppsala and Malmö." (PMID 39587192, 2024). "Endotoxin data correlated with a 60% (plus/minus) of the urinary kidney damage biomarkers (AGP, β2M, Cys-C, EGF and NGAL) evaluated and the redox activity to a 30% (plus/minus) with AGP and Cys-C." (PMID 27955691, 2016). "In particular, chronic administration of capsaicin on diabetic rats increased diuresis and the urinary excretion of the epidermal growth factor (EGF) but reduced the urinary levels of N-acetyl-b-D-glycosaminidase (NAG-L), a well-known biomarker of early kidney damage in DKD." (PMID 38255865, 2024). "This pathway has not been studied thoroughly in cisplatin-induced nephropathy although it was shown that cisplatin administration results in a decreased renal expression of EGF and a decreased urinary EGF excretion in the rat." (PMID 23457647, 2013).
renal cell carcinoma (13 papers, 1998 to 2025). "In fact, Dorai and others have demonstrated that the tyrosine moiety of CAIX present in its intracellular domain can be phosphorylated in an EGF-dependent manner in the renal cell carcinoma cell line SKRC-01." (PMID 39590368, 2024). "For instance, HIF-induced upregulation of the caveolin increased EGFR dimerization and phosphorylation, leading to EGF-independent activation of EGFR signaling in renal cell carcinoma cell lines." (PMID 35681691, 2022). "In conclusion, the results showed that EGF was highly expressed in renal cell cancer and higher expression of EGF was related with poor outcome in patients." (PMID 35655917, 2022). "In contrast, renal cell carcinoma expressed less bFGF (P<0.001) and EGF (P<0.001) than normal renal tissue." (PMID 17505508, 2007). "In breast cancer and renal cell carcinoma (RCC) autocrine signaling by CSF-1R was demonstrated in vivo and was modulated by TGFb1 and EGF, respectively." (PMID 27486763, 2016). "Thus changes in expression levels of EGF and TGFB1 in renal cells might modulate the renal cell carcinoma (RCC) development, in consequence of changes in regulatory elements of signaling networks such as the microRNAs (miRNAs)." (PMID 25909813, 2014).
renal fibrosis (13 papers, 2012 to 2025). A final common manifestation of a wide variety of chronic kidney diseases characterized by glomerulosclerosis and tubulointerstitial fibrosis. "As a result of the chronicity and progressive nature of renal fibrosis, longitudinal investigations are warranted to evaluate the clinical efficacy of urinary EGF measurements for cadmium-associated renal injury." (PMID 35011897, 2021). "EGF signaling has been implicated in the pathogenesis of pulmonary and renal fibrosis, but only little evidence exists for skin fibrosis." (PMID 34654463, 2021). "In previous studies, urinary EGF, a novel biomarker of renal fibrosis, was identified as an independent predictor of CKD progression, and the addition of urinary EGF to standard parameters could improve the prediction of disease events in diverse CKD populations." (PMID 35011897, 2021). "The urinary DKK-3, EGF, PRO-C6 levels were also significantly related to the extent of renal fibrosis." (PMID 37020541, 2023). "Blocking the TGF-β pathway or targeting EGF and PDGF receptors can prevent renal fibrosis." (PMID 39226168, 2024). "TGF-β serves as the main driving force of fibrosis progression in renal fibrosis, with epidermal growth factor (EGF) and platelet-derived growth factor (PDGF) acting as co-contributors, which have an important synergistic effect in the development of renal fibrosis." (PMID 39226168, 2024). "Furthermore, only the urinary DKK-3, EGF and PRO-C6 levels were significantly related to the extent of renal fibrosis." (PMID 37020541, 2023).
skin cancer (13 papers, 2014 to 2025). "Other potential targets for SWT identified in our study are AP-1 and NF-κB, which are transcription factors implicated in EGF-induced skin tumor promotion." (PMID 28335476, 2017). "Furthermore, chrysin is of antiproliferative activity causes cell cycle arrest on G1 phase and G1/S in skin cancer cell lines in EGF-stimulated JB6 P + cells." (PMID 36905557, 2023). "For instance, a study on Pongamia pinnata extract against skin cancer demonstrated that MD simulations were essential in verifying the stability of the complexes EGF-Pazopanib, EGFR-Pongachromene, and ERBB2-Vitexin up to 100 ns without any major fluctuation." (PMID 40627263, 2025). "Reports reveal that the anti-skin cancer effects of ISO are mediated through inhibiting the epidermal growth factor (EGF) induced neoplastic cell transformation." (PMID 38650631, 2024). "Since signaling through EGF and its receptor EGFR promotes skin cancer, EGF was used to promote the transformation of mouse epidermal cells JB6 P+ (the tumor promoter sensitive subline)." (PMID 35312729, 2022). "To experimentally verify this theoretical conclusion, we measured the STR of the epidermal growth factor (EGF)-related cascade in A431 skin cancer cells following stimulation with EGF using antibody microarrays against phosphorylated signal molecules." (PMID 36216834, 2022). "Our previous studies revealed that p38 MAPK plays an important role in EGF-induced cell transformation and skin cancer development by activating the AP-1 transcription factor." (PMID 26910280, 2016). "A431 skin cancer cells can be used to evaluate EGF signaling." (PMID 36216834, 2022). "Moreover, carvedilol-mediated inhibition of epidermal growth factor (EGF) promotion of JB6 P+ cells in soft agar mimics carvedilol-mediated attenuation of UV-induced skin tumors in mice." (PMID 31107911, 2019). "Kinases in the EGF-mediated signaling pathway are excellent targets for preventing skin cancer." (PMID 26910280, 2016). "Besides, ISO attenuated EGF-induced COX-2 expression in skin cancer JB6 and A431 cells." (PMID 38650631, 2024). "Among the tested EGF mutants (RS, SR), the GNP conjugate of the SR mutant showed enhanced biological activities and growth inhibition in EGFR-over expressing skin cancer cell line A431." (PMID 34512175, 2021). "EGF was used to promote transformation, because EGF and its receptor (EGFR) have been found as an important signaling pathway leading to cancer, including skin cancer." (PMID 28335476, 2017).
Hypertension (12 papers, 2010 to 2025). The presence of chronic increased pressure in the systemic arterial system. "The univariate analysis indicated that patients with AKI had a higher frequency of hypertension (odds ratio, OR = 11.42, 95% CI: 1.15–113, p = 0.037), and EGF > 4600 pg/mL was associated with a lower risk of AKI (OR = 0.05, 95% CI: 0.008–0.40; p = 0.004)." (PMID 36499745, 2022). "Previous research has demonstrated an association between concentrations of VEGF and EGF and hypertension, compared with healthy individuals." (PMID 27145079, 2016). "Moreover, elevated urinary levels of epidermal growth factor (EGF) have been linked to a reduced risk of hypertension over a 10-year period in relatively healthy middle-aged individuals." (PMID 40427524, 2025). "Examples of TKIs that result in arterial hypertension due to epidermal growth factor (EGF) inhibition are gefitinib and lenvatinib." (PMID 39653728, 2025). "On the other hand, EGFR is expressed in collecting ducts as well as in vascular cells, and infusion of EGF decreases epithelial sodium channel (ENaC) activity and prevents the development of hypertension and glomerular and tubular damage in Dahl SS rat strain." (PMID 40165104, 2025). "Hypertension progression was associated with VEGF-A, IL-6, IL-4, and MCP-3, while newly detected hypertension was linked to IL-9, TNFa, IL12(p40), IFNa2, and EGF." (PMID 37629267, 2023). "In contrast, T1DM mediated hypertension is accompanied with hyperfiltration followed by an increase in renin production which hypothetically could depress the tubular EGF production." (PMID 36996194, 2023). "The pathway enrichment analysis revealed the roles of the HIF-1-α transcription; endothelin; GPCR-binding ligand; and signaling pathways of EGF, PIk3, Arf6, S1P1, and PGDF in hypertension." (PMID 35205232, 2022).
Insulin resistance (12 papers, 2009 to 2025). Increased resistance towards insulin, that is, diminished effectiveness of insulin in reducing blood glucose levels. "EGF levels were significantly associated with IR suggesting a causative role of EGF on insulin resistance." (PMID 35956404, 2022). "Only a recent study has suggested a role for EGF in insulin resistance, showing an abnormal serum level in women with polycystic ovary syndrome." (PMID 35956404, 2022). "Furthermore, when correlating the Homeostatic Model Assessment for Insulin Resistance (HOMA-IR) with EGF, gender-dependent differences emerged in both healthy controls and diabetic patients." (PMID 38654922, 2024). "Besides, brown adipocyte-derived Neuregulin 4 (Nrg4), a member of the epidermal growth factor (EGF) family of ligands, attenuates hepatic lipogenic signaling and protects mice against diet-induced insulin resistance and hepatic steatosis." (PMID 37465124, 2023). "Furthermore, a crosstalk between insulin-induced ERK and epidermal growth factor (EGF) favored tumorigenesis by triggering the expression of anti-tumor immunity inhibitor programmed death-ligand 1 (PD-L1) in a cancer common in individuals with insulin resistance, pancreatic ductal adenocarcinoma." (PMID 36017326, 2022). "They concluded that ST are not markers of insulin resistance and it is possible that epidermal growth factor or other growth factors may play a role in the pathogenesis of the ST." (PMID 20049263, 2009). "Insulin resistance and altered adipokine signaling may disrupt epithelial metabolism and tear film homeostasis, while decreased levels of neurotrophic and growth factors such as NGF and epidermal growth factor (EGF) can impair corneal nerve regeneration and epithelial healing." (PMID 41303830, 2025).
myeloma (12 papers, 2014 to 2024). "In a second clinical trial of opaganib, 58% of patients with refractory multiple myeloma achieved stable disease or better, and patients had decreased plasma levels of TNFα, EGF and VEGF." (PMID 38069222, 2023). "The expression and/or activation of the epidermal growth factor (EGF) family of tyrosine kinase receptors, such as ErbB receptors, has been shown to be implicated in normal plasma cell differentiation and in myeloma biology." (PMID 25268740, 2014). "In conclusion, a total of 393 DEGs were identified between osteocytes co-cultured with and without myeloma cells, and KLF4, IRF8, EGF, EGR1, S1PR1, C3AR1, and NPY1R might be involved in osteocyte cell apoptosis induced by MM cells." (PMID 27405725, 2016). "Although, it is reported that protein kinase C (PKC) activation by the phorbol 12-myristate 13-acetate (PMA) induces SDC-1 shedding in myeloma cells and that its inhibition reverts this effect, PKC signaling cascade is not involved in EGF- and thrombin-mediated shedding." (PMID 24551591, 2014).
nasopharyngeal carcinoma (12 papers, 2010 to 2025). A carcinoma arising from the nasopharyngeal epithelium. "For example, 2-APB was shown to block EGF-induced cell migration in nasopharyngeal carcinoma and wound healing of clear cell renal cell carcinoma." (PMID 29507531, 2018). "In nasopharyngeal carcinoma, SPINK6 activates EGFR and downstream AKT pathway through a similar domain to EGF, enhancing EMT and thus promoting tumor metastasis." (PMID 39990675, 2025). "Keratinocyte-SFM is a complete serum-free medium supplemented with human recombinant Epidermal Growth Factor (rEGF) and Bovine Pituitary Extract (BPE), which has been successfully used to support the growth of primary nasopharyngeal epithelial cells and nasopharyngeal carcinoma cells." (PMID 27304186, 2016). "In nasopharyngeal carcinomas (NPC), TGF-β1 functions can be modulated from metastasis enhancer to tumor suppressor functions by the transcription factor FOXA1, showcasing dual functions of EMT regulators as will be discussed for EGF, too." (PMID 34771518, 2021).
oral mucositis (12 papers, 2009 to 2025). Inflammation of the mucous membranes of any of the structures in the mouth. "Regarding the role of EGF in oral mucosa in oncology, salivary EGF levels have been reported to be associated with the severity of oral mucositis induced by radiation therapy." (PMID 30290786, 2018). "Nal-P-113 promoted the repair of oral mucosal ulcers by increasing the EGF and FGF-2 expression and decreasing that of TGF-β1 in HIOECs, accelerating their proliferation and cell cycle progression." (PMID 30298136, 2018). "This study is the first to point out that supplementation of glycine in the oral mucositis model raises the expression of type I collagen, and quantitatively reduces the growth factors, EGF and PDGF." (PMID 30322002, 2018). "In patients with radiation-induced oral mucositis, salivary EGF levels were significantly lower and inversely correlated with the severity of oral mucositis." (PMID 29657585, 2018). "The aim of this study was to evaluate the efficacy and safety of recombinant human epidermal growth factor (rhEGF) oral spray for oral mucositis (OM) induced by intensive chemotherapy with hematopoietic stem cell transplantation." (PMID 28045958, 2017). "Patients with high concentrations of EGF in the saliva have been observed to recover more rapidly from oral mucositis than patients with low concentrations of EGF in the saliva, which suggests that EGF is associated with the healing process in the oral mucosa." (PMID 19456848, 2009). "Following topical treatment with EGF spray for 1 week, all of the patients showed improvements in oral mucositis, with significantly decreased mean RTOG grades (P = 0.0000)." (PMID 19456848, 2009). "EGF was measured with ELISA, and the severity of oral mucositis was reported." (PMID 41220465, 2025). "EGF was measured with ELISA, and radiotherapy-induced oral mucositis was evaluated with scores." (PMID 41220465, 2025). "Additionally, it has found that the severity of oral mucositis was positively correlated with the content of EGF in saliva." (PMID 36211346, 2022). "Although the mechanism of oral mucositis induced by the anti-EGFR antibody concomitant with 5-FU was not clarified, anti-EGFR therapy may deteriorate 5-FU-induced oral mucositis by interfering with the wound healing process due to blockage of EGF." (PMID 30290786, 2018). "In this study, we postulated that Nal-P-113 could shorten the healing time of oral mucosal ulcers by changing the expression of EGF, FGF-2, and TGF-β1 in human immortalized oral epithelial cells (HIOECs), which would accelerate the cell cycle and promote cell proliferation and migration." (PMID 30298136, 2018). "Recombinant human EGF (rhEGF) has been shown to enhance the mucosal wound healing process, which suggests that it may be effective in the treatment of radiation-induced oral mucositis." (PMID 19456848, 2009). "During chronic oral mucositis of mechanical, chemical, or microbial origin, leukocytes and macrophages are recruited in the damaged mucosa, where they produce cytokines such as interleukin-1, -6, and -8, tumor necrosis factors, transforming growth factor (TGF)-β1, and epidermal growth factor (EGF)." (PMID 39120324, 2024).